DEFB132 (defensin beta 132)
Description:
Has antibacterial activity.
Synonyms: BD-32; DEFB-32; DEFB32; RP5-1103G7.6; HEL-75; KFLL827; UNQ827
Tractability: Antibody: UniProt places it where antibodies can reach, with high confidence; UniProt predicts a signal peptide or a membrane-spanning region; its Gene Ontology location is reachable by antibodies, with medium confidence.
Gene: Protein-coding gene on chromosome 20 (257,724 to 261,096, forward strand). Ensembl gene ENSG00000186458.
Subcellular location: Secreted
Pathways (Reactome):
Immune System: Beta defensins; Defensins
Gene Ontology:
Molecular function: protein binding
Biological process: killing of cells of another organism; defense response to Gram-negative bacterium; innate immune response
Cellular component: extracellular region; sperm head
Genetic constraint (gnomAD): Loss-of-function variants: 5 observed, 2.85 expected, observed/expected ratio (o/e) 1.75, 90% interval 0.77 to 1.95. That is too few expected variants to judge how well the gene tolerates losing a copy. Missense variants: 110 observed, 107.64 expected, observed/expected ratio (o/e) 1.02, 90% interval 0.88 to 1.2. Synonymous variants: 50 observed, 46.31 expected, observed/expected ratio (o/e) 1.08, 90% interval 0.86 to 1.37.
Homologues: Orthologues: macaque DEFB132 (86% identical), mouse Defb22 (21% identical), mouse Defb15 (18% identical), mouse Defb34 (18% identical), rat Defb22 (18% identical), rat Defb15 (17% identical). Paralogues in human: DEFB118 (33% identical), DEFB121 (26% identical), DEFB123 (25% identical), DEFB125 (25% identical), DEFB128 (25% identical), DEFB124 (24% identical), DEFB127 (22% identical), DEFB129 (22% identical), DEFB108B (21% identical), DEFB108C (21% identical), DEFB116 (21% identical), DEFB115 (20% identical), and 7 more.
Diseases named in the same sentence as DEFB132 in open-access papers:
DEFB132 is named in the same sentence as 1 disease in open-access papers, as found by Europe PMC text mining. Sharing a sentence is not in itself a finding about the gene and the disease. The quoted sentences say what the papers report.
squamous carcinomas (1 paper, 2025). "Among the most significantly downregulated transcripts in later stage tumors are DEFB132 (a defensin involved in innate immunity), C14orf180 (an integral plasma membrane protein), TMEM252 (an integral plasma membrane protein), and LINC01537, an LncRNA associated with squamous carcinomas." (PMID 41224793, 2025).